GPSM2 (G protein signaling modulator 2)
Diseases named in the same sentence as GPSM2 in open-access papers (continued):
Sharing a sentence is not in itself a finding about the gene and the disease.
Cerebellar dysplasia (1 paper, 2025). Cerebellar dysplasia (abnormal growth or development) is defined by abnormal cerebellar foliation, white matter arborization, and gray-white matter junction. "Mutations in Gpsm2 cause the human disease Chudley‐McCullough syndrome, a developmental disorder characterized by sensorineural deafness and a particular set of brain anomalies (agenesis of the corpus callosum, cerebellar dysplasia, and nodular heterotopia)." (PMID 41250748, 2025).
colorectal adenocarcinoma (1 paper, 2024). The most common type of colorectal carcinoma. "The analysis of TIMER2 revealed that GPSM2 is significantly overexpressed in all gastrointestinal (GI) cancers, including colorectal adenocarcinoma (COAD), esophageal squamous cell carcinoma (ESCA), pancreatic adenocarcinoma (PAAD), renal cell carcinoma (READ), and stomach adenocarcinoma (STAD)." (PMID 38674408, 2024).
gastric cancer (1 paper, 2024). A primary or metastatic malignant neoplasm involving the stomach. "Additionally, GPSM2 overexpression correlated with lower overall survival, progression-free survival, and pathologic complete response of gastric cancer patients." (PMID 38674408, 2024). "Further analysis using the Kaplan–Meier plotter tool demonstrated that a high expression of GPSM2 is associated with low OS (p = 9 × 10−14), false-positive (FP) results (p = 7.9 × 10−10), and progression-free survival (PPS) (p = 2.7 × 10−10) in gastric cancer patients." (PMID 38674408, 2024).
Hydrocephalus (1 paper, 2021). Hydrocephalus is an active distension of the ventricular system of the brain resulting from inadequate passage of CSF from its point of production within the cerebral ventricles to its point of absorption into the systemic circulation. "Hydrocephalus was detected in our patient, which is a condition that has previously been reported in some patients with GPSM2 pathogenic variants." (PMID 34062854, 2021).
lymph node metastasis (1 paper, 2020). "Furthermore, a chi-square test showed that high GPSM2 expression was significantly correlated with increased T stage (p = 0.029), lymph node metastasis (p = 0.002), and higher TNM stage (p < 0.001)." (PMID 32195179, 2020). "Furthermore, a chi-square test showed that compared with GPSM2-cytoplasm group, GPSM2-nucleus group was significantly correlated with HER2 receptor-positive (p = 0.010), Ki67-positive (p = 0.001), increased T stage (p = 0.001), lymph node metastasis (p = 0.015), and higher TNM stage (p = 0.029)." (PMID 32195179, 2020).
microcephaly (1 paper, 2021). A congenital or acquired developmental disorder in which the circumference of the head is smaller than normal for the person's age and sex. "Even though the cytocortical proteins help to orientate the mitotic spindle, the loss of GPSM2 does not lead to microcephaly despite the randomized cleavage planes in dividing neural progenitors." (PMID 33899739, 2021).
retinal disease (1 paper, 2012). "Based on putative function and/or involvement in retinal disease, we selected 16 genes – Bach2, Cdr2, Dusp12, Esrrb, Gpsm2, Haus1, Kdm5b, Lman1, Lrp11, Lrrc2, Ncoa2, Plekha2, Ppargc1b, Trim36, Wisp1 and Zdhhc14." (PMID 22511886, 2012).
rheumatoid arthritis (1 paper, 2022). A chronic, systemic autoimmune disorder characterized by inflammation in the synovial membranes and articular surfaces. "Studies have shown that GPSM2 expression decreases CD4 T+ cells in rheumatoid arthritis patients and can act as a promoter of regular T cell migration in healthy individuals." (PMID 36186420, 2022).
triple-negative breast carcinoma (1 paper, 2021). An invasive breast carcinoma which is negative for expression of estrogen receptor (ER), progesterone receptor (PR), and human epidermal growth factor receptor 2 (HER2). "GPSM1, GPSM2, and GPSM3 were most highly expressed in triple negative breast cancer cell lines, while GPSM4 showed high expression in multiple luminal A cell lines." (PMID 34572330, 2021).
Usher syndrome (1 paper, 2018). A syndromic diseae characterized by the association of sensorineural deafness (usually congenital) with retinitis pigmentosa and progressive vision loss. "The location of CLCC1 alongside GPSM2, which codes for the putative whirlin protein complex-interacting molecule, is interesting given the role of this complex in Usher syndrome." (PMID 30157172, 2018).
uterine corpus endometrial carcinoma (1 paper, 2022). A endometrial carcinoma (disease) that involves the body of uterus. "We identified GPSM2 mutation loci with the highest frequency of mutations in uterine corpus endometrial carcinoma (UCEC), and this mutation increased progression-free survival and overall survival in uterine corpus endometrial carcinoma patients." (PMID 36186420, 2022).
cancer (10 papers, 2013 to 2025). A tumor composed of atypical neoplastic, often pleomorphic cells that invade other tissues. "Gpsm2 plays a pivotal role in cellular and developmental processes, and upregulation is linked to increased cancer risk." (PMID 41250748, 2025). "In summary, our comprehensive pan-cancer analysis of GPSM2 revealed an association between GPSM2 expression and clinical prognosis, protein phosphorylation, immune cell infiltration, tumor mutation burden, and microsatellite instability in human cancers." (PMID 36186420, 2022). "The results showed that GPSM2 expression was positively correlated with the estimated cancer-associated fibroblast infiltration value in PRAD and negatively correlated with BRCA." (PMID 36186420, 2022). "The results showed that GPSM2 expression was positively correlated with cancer-associated fibroblast infiltration in PRAD and negatively correlated with BRCA." (PMID 36186420, 2022). "GPSM2, G-protein-signaling modulator 2, belongs to a family of genes that modulate G proteins activation and is associated with cell division and cancer." (PMID 23741398, 2013). "Secondly, increased expression of GPSM2 has been linked to a poorer prognosis in cancer patients." (PMID 38674408, 2024). "In addition, we found that GPSM2 overexpression was associated with poor prognosis in cancer patients (e.g., ACC and LIHC)." (PMID 36186420, 2022). "In contrast, a decline in GPSM2 gene expression in non-small cell lung cancer (NSCLC) suggests a protective effect of this gene against cancer metastasis." (PMID 38674408, 2024). "G protein-signaling modulator 2 (GPSM2) has been identified as a crucial factor in the progression of cancer." (PMID 38674408, 2024). "Its transcript and protein levels typically increase significantly in most tumors, indicating a cancer-promoting role for GPSM2." (PMID 38674408, 2024). "Recent investigations have highlighted the importance of the GPSM family, particularly GPSM2, in various cancer types." (PMID 38674408, 2024). "The involvement of GPSM2 in cancer can be understood through several aspects: Initially, GPSM2 is frequently overexpressed in most tumors versus healthy controls." (PMID 38674408, 2024). "This study investigates the G-protein signaling modulator (GPSM) family across several cancers and presents a comprehensive pan-cancer analysis of the GPSM2 gene across several gastrointestinal (GI) cancers." (PMID 38674408, 2024). "Subsequent studies on the GPSM2 gene in gastrointestinal cancers included a pan-cancer analysis across ESCA, PAAD, READ, and STAD cancers, demonstrating significant GPSM2 overexpression across all." (PMID 38674408, 2024). "To explore the GPSM2 expression profile in pan-cancer analysis, we used a dataset from The Cancer Genome Atlas (TCGA) database." (PMID 36186420, 2022). "We know that the GPSM2 protein level in most cancers is higher than in corresponding normal tissues." (PMID 36186420, 2022). "We performed pathway GO|KEGG pathway enrichment analysis of similar genes to explore the specific mechanism of GPSM2 in cancer." (PMID 36186420, 2022). "This comprehensive analysis helps reveal the GPSM2 mechanism in human tumors, which is also helpful in predicting tumor prognosis and providing implications for targeted cancer therapy." (PMID 36186420, 2022). "The study sample should be expanded in the future to ensure its reliability and further investigate the specific mechanisms between GPSM2 and cancers by clinical samples." (PMID 36186420, 2022). "We found that the transcript and protein levels of GPSM2 were increased in most tumors compared to normal tissues (e.g., OV and THYM), suggesting a pro-cancer role for GPSM2 in most tumors." (PMID 36186420, 2022). "The TIMER algorithm was used to explore the correlation between the cancer-associated fibroblast, neutrophil, endothelial cell infiltration level and GPSM2 expression in TCGA pan-cancer." (PMID 36186420, 2022).
cancer (continued). "Then, through the GPSM2 expression data in GEPIA2+TCGA pan-cancer, the top 100 genes with the strongest correlation with GPSM2 expression were screened." (PMID 36186420, 2022). "Several studies have highlighted the significance of GPSM2 in cancer development." (PMID 38674408, 2024). "In conclusion, our findings demonstrate the important value of GPSM2 as a potential cancer marker." (PMID 36186420, 2022). "Therefore, we used the GEPIA2 dataset to evaluate the total protein content of GPSM2 across cancers." (PMID 36186420, 2022). "Therefore, we explored the relationship between GPSM2 expression and cancer-infiltrating immune cells." (PMID 36186420, 2022). "In this study, we have confirmed the clinical value of GPSM2.Thus, GPSM2 may be a promising target for new cancer therapy through regulating GPCRs pathway." (PMID 32195179, 2020). "Since no GPSM2 phosphorylation site has been reported to be associated with cancer, we may be the first to report a phosphorylation site." (PMID 36186420, 2022). "Furthermore, it appears that GPSM2, through the “PBK/TOPK-LGN/GPSM2” pathway, can significantly contribute to cell growth, making it a potential target for cancer therapy." (PMID 38674408, 2024). "The expression differences were divided into four categories: 1) GPSM2 expression in cancer tissues was higher than in adjacent normal tissues." (PMID 36186420, 2022).
tumor (8 papers, 2020 to 2026). "The elevated expression of GPSM2 is linked to larger tumor sizes and HBV infection." (PMID 38674408, 2024). "In addition, we investigated GPSM2 gene mutations in human tumor specimens and the impact of gene mutations on patient survival." (PMID 36186420, 2022). "This elucidates the impact of GPSM2 on tumor prognosis at the genetic level, and inhibition of the GPSM2 gene R17C mutation might be effective in suppressing UCEC disease progression, which is only speculation and hypothesis at present." (PMID 36186420, 2022). "G-protein signalling modulator 2 (GPSM2), a member of the G-protein signalling regulator family, is highly expressed in various tumour tissues; however, its role in pancreatic cancer remains largely undefined." (PMID 42231052, 2026). "Analysis of GPSM2 expression concerning tumor purity demonstrated highly positive correlation and correlations with the infiltration levels of CD4+ T cells and macrophages within CRC." (PMID 38674408, 2024). "This validation involved quantitative real-time PCR (qRT-PCR) to assess the mRNA expression levels of GPSM2 within the tumor samples." (PMID 38674408, 2024). "Functional enrichment analysis underscores the involvement of GPSM2 in vital pathways, indicating its role in tumor progression." (PMID 38674408, 2024). "GPSM2 expression in LIHC, KIRC, BRCA, COAD, OV and STAD was significantly increased, but GPSM2 expression in PRAD was lower than that in normal tissues (we selected immunohistochemical images with >75% tumor cells and moderate or vigorous staining)." (PMID 36186420, 2022). "Second, we analyzed the GPSM2 phosphorylation level using the clinical proteomic tumor analysis consortium dataset." (PMID 36186420, 2022). "Meanwhile, many studies have reported that GPSM2 can be identified as a prognostic factor in LIHC that promotes tumor proliferation and metastasis." (PMID 36186420, 2022). "Immune cell infiltration is considered an essential factor in tumor development, and our findings are complementary to the report that GPSM2 affects tumor progression through resistant action." (PMID 36186420, 2022). "The results of phosphorylation analysis suggest that tumor development involves a complex GPSM2 phosphorylation process." (PMID 36186420, 2022). "Five prognostic factors, T stage, M stage, pathologic stage, tumor status, and GPSM2 expression, were included in the model." (PMID 36186420, 2022). "Furthermore, GPSM2 has the capacity to modulate immune cell infiltration in the tumor microenvironment and promote tumor cell migration." (PMID 38674408, 2024). "Lastly, the expression and function of GPSM2 appear to vary depending on the type of tumor." (PMID 38674408, 2024). "Furthermore, significant correlations between GPSM2 expression and immune cell infiltration are observed, suggesting its involvement in tumor immune evasion mechanisms." (PMID 38674408, 2024). "Additionally, the gene’s involvement in cell migration and immune cell infiltration within the tumor microenvironment was emphasized, considering GPSM2 as a prognostic marker and potential therapeutic target in PAAD." (PMID 38674408, 2024). "In addition, GPSM2 can affect the infiltration of immune cells in the tumor microenvironment and promote tumor cell migration." (PMID 36186420, 2022). "Therefore, we analyzed the GPSM2 phosphorylation degree between normal and tumor tissues by the CPTAC dataset and screened five tumor tissues with meaningful differences." (PMID 36186420, 2022). "Therefore, studying GPSM2 gene changes in human tumor samples will help us clarify tumor pathogenesis and select therapeutic targets." (PMID 36186420, 2022). "Nevertheless, the expression and function of GPSM2 depend on different tumor types." (PMID 36186420, 2022). "In addition, we investigated the correlation between GPSM2 expression and prognosis in different clinical subgroups (T stage, M stage, pathological stage, tumor status) of LIHC." (PMID 36186420, 2022).
tumor (continued). "Additionally, GPSM2 contributes to maintaining cell polarity and spindle orientation during mitosis, which could potentially influence tumor growth and progression." (PMID 38674408, 2024). "TIMER analysis revealed that GPSM1, GPSM2, and GPSM4 were only slightly correlated with tumor purity and infiltrating lymphocytes (correlation coefficients ranging from approximately −0.3 to 0.2)." (PMID 34572330, 2021). "Based on the action mechanism of miRNA on mRNA and putative oncogenic roles of CELSR3, GPSM2, and CHEK1, potential miRNAs should be tumor suppressive miRNAs and should be negatively correlated with CELSR3, GPSM2, or CHEK1." (PMID 32257949, 2020). "Among them, the expression of CNR2, GIP, GNGT1, NPY1R, SSTR5, and LEP in tumor tissue was significantly lower than in normal tissue, while the expression of GPSM2, and NMU was significantly highly expressed in tumor tissue." (PMID 33169793, 2020). "We found that GPSM2 was highly expressed in DLBC, LGG, OV, SARC and THYM tumor tissues (p < 0.05)." (PMID 36186420, 2022). "We speculate that this is mainly because nuclear localization of GPSM2 is unavailable to inhibit activity of Gα protein that is expressed on the membrane, thereby enhancing the activity of the GPCR pathway and promoting tumor progression." (PMID 32195179, 2020).
GPSM2 also shares sentences with these, for which no sentence is quoted: cyst (2 papers); Ewing sarcoma (2); infection (2); neurological diseases (2); cone-rod dystrophy (1); epilepsy (1); esophageal squamous cell carcinoma (1); head and neck squamous cell carcinoma (1); lung carcinoma (1); nodular heterotopia (1); pancreatic adenocarcinoma (1); pituitary hormone deficiency (1); prostate adenocarcinoma (1); renal cell carcinoma (1); X-linked dominant orofaciodigital syndrome (1).